RNU6-964P (RNA, U6 small nuclear 964, pseudogene)
Gene: Small nuclear RNA gene on chromosome 2 (229,937,814 to 229,937,882, reverse strand). Ensembl gene ENSG00000252333.
Homologues: Orthologues: chimpanzee U6 (99% identical), macaque U6 (93% identical), rat LOC120103203 (91% identical), guinea pig U6 (87% identical), dog U6 (84% identical), guinea pig U6 (80% identical). Paralogues in human: RNU6-17P (94% identical), RNU6-18P (94% identical), RNU6-33P (94% identical), RNU6-1 (93% identical), RNU6-1122P (93% identical), RNU6-11P (93% identical), RNU6-12P (93% identical), RNU6-13P (93% identical), RNU6-2 (93% identical), RNU6-22P (93% identical), RNU6-25P (93% identical), RNU6-32P (93% identical), and 1284 more.